TRPV3 (transient receptor potential cation channel subfamily V member 3)
Description:
Non-selective calcium permeant cation channel. It is activated by innocuous (warm) temperatures and shows an increased response at noxious temperatures greater than 39 degrees Celsius. Activation exhibits an outward rectification. The channel pore can dilate to provide permeability to larger cations. May associate with TRPV1 and may modulate its activity. Is a negative regulator of hair growth and cycling: TRPV3-coupled signaling suppresses keratinocyte proliferation in hair follicles and induces apoptosis and premature hair follicle regression (catagen).
Synonyms: VRL3; FNEPPK2; OLMS; OLMS1
Tractability: Small molecule: a drug acting on it is in phase 2 or 3 trials; a structure with a bound ligand is known; a high-quality ligand is known; it belongs to a druggable protein family. Antibody: UniProt places it where antibodies can reach, with high confidence; its Gene Ontology location is reachable by antibodies, with high confidence; UniProt predicts a signal peptide or a membrane-spanning region; the Human Protein Atlas places it where antibodies can reach. PROTAC: ubiquitination databases record sites on it; a small molecule that binds it is known.
Target class: Voltage-gated ion channel; Ion channel; Transient receptor potential channel
Gene: Protein-coding gene on chromosome 17 (3,510,502 to 3,557,812, reverse strand). Ensembl gene ENSG00000167723.
Subcellular location: Cell membrane; Cytoplasm; Lysosome
Subcellular location (Human Protein Atlas): Plasma membrane; Centrosome; Cytosol
Pathways (Reactome):
Transport of small molecules: TRP channels
Gene Ontology:
Molecular function: calcium channel activity; identical protein binding; protein binding; sodium channel activity; calcium ion transmembrane transporter activity; monoatomic cation channel activity; monoatomic ion channel activity
Biological process: negative regulation of hair cycle; actin filament organization; calcium ion import across plasma membrane; calcium ion transmembrane transport; osmosensory signaling pathway; monoatomic ion transport; positive regulation of calcium ion import; sodium ion transmembrane transport
Cellular component: cytoplasm; lysosome; plasma membrane; receptor complex; cilium; membrane
Genetic constraint (gnomAD): Loss-of-function variants: 80 observed, 78.05 expected, observed/expected ratio (o/e) 1.02, 90% interval 0.86 to 1.24. The upper end of that interval is the gene's LOEUF score, 1.24, which puts it in group 5 of 6, group 1 being the genes least tolerant of losing a copy. Missense variants: 994 observed, 993.38 expected, observed/expected ratio (o/e) 1, 90% interval 0.95 to 1.05. Synonymous variants: 420 observed, 417.66 expected, observed/expected ratio (o/e) 1.01, 90% interval 0.93 to 1.09.
Homologues: Orthologues: chimpanzee TRPV3 (98% identical), macaque TRPV3 (97% identical), pig TRPV3 (95% identical), dog TRPV3 (94% identical), rat Trpv3 (93% identical), mouse Trpv3 (93% identical), guinea pig TRPV3 (93% identical), rabbit TRPV3 (77% identical), tropical clawed frog trpv3 (59% identical), Caenorhabditis elegans ocr-4 (21% identical), Drosophila melanogaster iav (20% identical), Drosophila melanogaster nan (20% identical), and 1 more. Paralogues in human: TRPV4 (39% identical), TRPV1 (39% identical), TRPV2 (36% identical), TRPV6 (23% identical), TRPV5 (23% identical).
Diseases named in the same sentence as TRPV3 in open-access papers:
TRPV3 is named in the same sentence as 98 diseases in open-access papers, as found by Europe PMC text mining. Sharing a sentence is not in itself a finding about the gene and the disease. The quoted sentences say what the papers report.
Olmsted syndrome (38 papers, 2012 to 2026). A hereditary palmoplantar keratoderma characterized by the combination of bilateral mutilating transgredient palmoplantar keratoderma and periorificial keratotic plaques. "Specifically, PVLP-delivered SaCas9 and shRNA effectively disrupted the Trpv3 gene or reduced its expression, leading to decreased TRPV3 activity and mitigating the hyperactivity associated with Olmsted syndrome." (PMID 40171279, 2025). "Recent findings of various mutations in human TRPV3 associated with Olmsted Syndrome further emphasize the significance of TRPV3 activity in the development of keratinocytes." (PMID 39926429, 2025). "We further showed that PVLPs can be used for gene therapy for Olmsted syndrome, a genetic skin disease caused by a gain-of-function mutation in the Trpv3 gene." (PMID 40171279, 2025). "Studies have revealed that Olmsted Syndrome’s pathogenesis arises from acquired functional mutations in the TRPV3 gene, causing heightened Ca2+ influx into keratinocytes." (PMID 39926429, 2025). "Olmsted syndrome is caused by a single point mutation in Trpv3, recapitulated by Gly573Ser in the DS-Nh mouse model." (PMID 40171279, 2025). "In fact, TRPV3 mutations associated with a variety of integumentary diseases such as Olmsted’s syndrome while increased gene expression was observed in several types of cancer and cardiac diseases." (PMID 38365607, 2024). "TRPV3 mutations were also suggested to drive hair loss in patients with Olmsted syndrome (OMIM#614,594) [reviewed in 28]." (PMID 38365607, 2024). "Here, we report a Chinese case of Olmsted syndrome associated with a novel missense mutation in TRPV3, p.Val306Met." (PMID 39469632, 2024). "Electrophysiological experiments have demonstrated that gain-of-function mutations in TRPV3 can exert significant pathogenic effects on protein function, leading to the characteristic pathological phenotype of Olmsted syndrome (OS)." (PMID 39469632, 2024). "After treatment with Erlotinib, palmoplantar keratosis in patients with Olmsted syndrome caused by TRPV3 mutations was improved, and TRPV3 signaling leads to EGFR transactivation." (PMID 38706904, 2024). "TRPV3-determined Olmsted syndrome is associated with more than 20 amino acid substitutions that lead to the channel gain-of-function." (PMID 37239947, 2023). "Among the TRPV family channels, it is well known that TRPV3 is involved in the differentiation of keratinocytes and its pathologic activity or genetic mutations are associated with skin disorders such as Olmsted syndrome." (PMID 36827119, 2023). "Individuals with Olmsted syndrome also have the following mutation variants: TRPV3 Gly573Ser and Trp692Gly." (PMID 37185752, 2023). "This study investigated the TRPV3-inhibitory properties of alpha-mangostin on TRPV3 hyperactive mutants associated with Olmsted syndrome and its impact on TRPV3-induced cytokine secretion and cell death." (PMID 37629111, 2023). "In mice, a gain of function mutation of TRPV3 caused a hairless phenotype with itchy skin, while in humans with Olmsted syndrome (OS), gain of function mutants cause severe palmoplantar hyperkeratosis." (PMID 34664138, 2021). "Gain-of-function mutations of TRPV3 cause hair growth disorders in mice and Olmsted syndrome in humans." (PMID 33876725, 2021). "In humans, gain-of-function genetic mutations of TRPV3 cause Olmsted syndrome, which is clinically characterized by diffuse palmoplantar keratoderma, alopecia, and skin inflammation." (PMID 35058747, 2021). "In human, gain-of-function mutations of TRPV3 are associated with Olmsted syndrome, which is characterized by severe itch and palmoplantar and periorificial keratoderma." (PMID 32694980, 2020). "RT-PCR or q-PCR analysis showing the absence of TRPV3 in human BMECs and gain-of-function mutations in human TRPV3 are associated with Olmsted syndrome, which is characterized by severe palmoplantar and periorificial keratoderma." (PMID 33262985, 2020).
Olmsted syndrome (continued). "Gain-of-function mutations in human TRPV3 from patients with Olmsted syndrome (OS) suggest a role of TRPV3 in human itch signaling." (PMID 30301231, 2018). "Mutation of the corresponding W673 in TRPV3 results in Olmsted syndrome, and replacement of the corresponding residue in NOMPC results in a channel that has increased current amplitude but is nonresponsive to mechanical stimuli." (PMID 29726814, 2018). "In 2012, whole-exome sequencing of six patients with Olmsted Syndrome revealed a TRPV3 mutation is strongly associated with this disease." (PMID 27983625, 2016). "More recently, similar gain-of-function mutations in TRPV3, including but not limited to the Gly573 mutation, have been identified as the cause of Olmsted syndrome (OS) in humans." (PMID 27618069, 2016). "A recent study identified de novo mutations causing constitutive activation of TRPV3 as a cause of the keratotic manifestations of Olmsted syndrome." (PMID 23692804, 2013). "The TRPV3 channel is crucial for skin barrier formation and hair growth, and its dysregulation is linked to itch, atopic dermatitis, rosacea, and genetic disorders like Olmsted syndrome." (PMID 41787805, 2026). "While TRPV3 Gly573 mutation mice indicated the involvement of TRPV3 in itch, the Gly573 missense mutation was also discovered in Olmsted syndrome, which is a rare congenital disease characterized by skin hyperplasia, diffuse palmoplantar keratoderma, alopecia, and severe pruritus." (PMID 38254707, 2024). "TRPV3 is robustly linked to a rare hereditary disease named Olmsted syndrome (OS)." (PMID 37239947, 2023). "Moreover, excessive TRPV3 activity was shown to be associated with inflammation and itches in Olmsted syndrome." (PMID 37629111, 2023). "In addition, the mutation of the TRPV3 gene has been found to be responsible for the occurrence of diseases such as atopic dermatitis (AD) and Olmsted syndrome (OS)." (PMID 36979447, 2023). "Skin pathology is also related to TRPV3 channels, as verified by experimental results showing that ‘gain-of-function’ mutations in TRPV3 are associated with atopic dermatitis and Olmsted syndrome, and that alterations in TRPV3 expression level cause rosacea and psoriasis." (PMID 37344508, 2023). "A homozygous gain-of-function 1562G>C variant of the TRPV3 may be involved in the development of Olmsted syndrome." (PMID 37185752, 2023). "Additionally, patients suffering from Olmsted syndrome display genetic heterogeneity where different naturally occurring mutations in the TRPV3 gene show similar phenotypes along with clinical heterogeneity." (PMID 35058747, 2021). "Gain-of-function mutations in the Trpv3 gene, including the G573S point mutation, cause a form of palmoplantar keratoderma known as Olmsted syndrome, an autosomal dominant genodermatoses phenotypically characterized by palmoplantar keratoderma and periorificial keratotic plaques." (PMID 35058747, 2021). "Mutations of TRPV3 lead to severe dermal hyperkeratosis in Olmsted syndrome, but whether the mutants are trafficked to the cell membrane or not is controversial." (PMID 34664138, 2021). "Human Olmsted syndrome has been linked to the gain-of-function mutations of TRPV3." (PMID 33876725, 2021). "TRPV3 dysfunction caused by genetic gain-of-function mutations or pharmaceutical activation has been linked to human skin diseases, including genodermatosis known as Olmsted syndrome and erythromelalgia." (PMID 33876725, 2021). "Remarkably, the G573S mutation of human TRPV3 corresponding to mouse TRPV3-G573S in our study is associated with Olmsted syndrome, which is characterized by bilateral mutilating palmoplantar keratoderma and periodic keratotic plaques accompanied by severe itching." (PMID 33674682, 2021).
Olmsted syndrome (continued). "In summary, we are making headway in understanding the role of TRPV3 in health and disease and this appears to be a promising therapeutic target for itch and skin-related conditions and for the treatment of patients with TRPV3 causally related conditions, such as Olmsted syndrome." (PMID 27618069, 2016). "Olmsted syndrome, given its well-defined etiology and the general innocuity of Trpv3 KO in mice, stands out as a promising target for gene therapy." (PMID 40171279, 2025). "The clearest link exists between Olmsted syndrome (OLMS1, OMIM 614594), a rare congenital disorder, and GOF mutations in TRPV3, as demonstrated in a series of clinical reports." (PMID 41118703, 2025). "PVLPs deliver gene-editing tools to treat Olmsted syndrome, reducing TRPV3 hyperactivity and hyperkeratosis." (PMID 40171279, 2025). "This review will lay a foundation for further developing the individualized treatment for TRPV3-related Olmsted syndrome." (PMID 39748945, 2024). "Some gain-of-function variations in TRPV3 have been reported in patients with hereditary Olmsted syndrome, a rare hyperkeratotic skin channelopathy." (PMID 38062125, 2023). "TRPV3 channels also play a critical role in skin physiology, including skin barrier formation, hair growth, wound healing, Olmsted syndrome, skin pain and itching." (PMID 36677834, 2023). "TRPV3 found great attention in dermatology, a human gain-of-function mutation is in part responsible for the hyperkeratotic and mutilating Olmsted syndrome; TRPV3 plays roles in the control of hair growth and lipid secretion, in atopic dermatitis and pruritus." (PMID 35157132, 2022). "Genetic studies of TRPV3 channels include Olmsted syndrome (OS), a rare hyperkeratotic skin channelopathy of TRPV3 gain-of-function changes." (PMID 36499288, 2022). "The discovery of the link between Olmsted Syndrome and TRPV3 led to additional genetic studies in this condition." (PMID 27983625, 2016). "The symptoms of Olmsted syndrome are thought to be related to the TRPV3/EGFR signaling pathway." (PMID 37239947, 2023). "The use of TRPV3 antagonists could represent a novel targeted strategy for relieving Olmsted syndrome symptoms." (PMID 37239947, 2023). "In an attempt to explain the hyperkeratosis found in Olmsted syndrome, a simple hypothesis suggests that a higher influx of Ca2+ through mutant TRPV3 leads to apoptosis." (PMID 34664138, 2021). "Finally, given the therapeutic potential of MuPVLP delivery of shRNAs, we investigated whether Trpv3-shRNA could mitigate the Olmsted syndrome phenotype in skin equivalents." (PMID 40171279, 2025). "A large number of studies have shown that the topical application of TRPV3 inhibitors can effectively inhibit skin pruritus and pain, which provides a new idea for the treatment of intractable pruritus and pain diseases such as Olmsted syndrome and hereditary palmoplantar keratosis." (PMID 36677834, 2023). "Gain-of-function mutations in human TRPV3 can lead to the Olmsted syndrome, which is characterized by a severe periorificial and palmoplantar keratoderma without affecting cerebral functions, suggesting a lack of function for TRPV3 in the brain." (PMID 33806707, 2021). "Also, TRPV3 mutations in the linker region between S4 and S5 and in the TRP-box cause the Olmsted syndrome (congenital palmoplantar and periorificial keratoderma, alopecia, and itching), highlighting the importance of transmembrane and C-terminal domain for the function of TRP channels." (PMID 29736621, 2018). "Notably, the gain-of-function mutations that cause Olmsted syndrome are located in the S4−S5 linker and its junctions with the S4b, S3, the TRP domain, and the lower part of S6, underscoring the importance of the S4–S5 linker in TRPV3 channel gating." (PMID 30429472, 2018). "Finally, targeting Trpv3 via PVLP delivery of SaCas9 or shRNA was remarkably efficient in primary keratinocytes and resulted in rescue of Olmsted syndrome phenotypes in ex vivo mouse skin equivalents." (PMID 40171279, 2025).
Olmsted syndrome (continued). "However, it has been speculated that the pathophysiology of Olmsted syndrome might not be explained solely by abnormal TRPV3 function in keratinocytes, but may also involve immune dysfunction arising in other cells such as cutaneous Langerhans cells." (PMID 34489697, 2021).
dermatitis (28 papers, 2009 to 2026). An inflammatory process affecting the skin. "Overactivity of TRPV3 function has been implicated in the pathology of Olmsted syndrome, chronic pruritus, alopecia and dermatitis." (PMID 40699677, 2025). "Gain-of-function mutations of TRPV3 in keratinocytes are closely associated with skin barrier imbalance, wound healing, pruritus, dermatitis, alopecia, and genetic Olmsted syndrome (OS)." (PMID 40409547, 2025). "Overactive TRPV3 channels are implicated in various skin diseases including OS, itching, dermatitis, hair growth, and wound healing." (PMID 40409547, 2025). "Constitutive activation of TRPV3 due to continuous stimulation or the presence of Olmsted mutations causes noticeable skin inflammation due to the increased secretion of pro-inflammatory cytokines from the keratinocytes." (PMID 37629111, 2023). "In rodents, a sponateous gain-of-function matation of the TRPV3 gene causes the development of skin lesions with pruritus and dermatitis." (PMID 38123150, 2023). "The overexpression of TRPV3 can lead to hair loss, skin inflammation, severe pruritus and dermatitis." (PMID 36677834, 2023). "Mutations for Gly573Ser and Gly573Cys in the TRPV3 gene displayed a hairless or pruritic dermatitis phenotype in rodents." (PMID 35813831, 2022). "TRPV3 is highly expressed in skin keratinocytes, whose hyperactivity causes pruritic dermatitis and scratching behavior." (PMID 33876725, 2021). "In general, TRPV3 seems to be important for the health of the skin, and loss of TRPV3 function leads to skin inflammations, dermatitis, itchiness and hair loss." (PMID 34356643, 2021). "The multimodal sensory channel transient receptor potential vanilloid-3 (TRPV3) is expressed in epidermal keratinocytes and implicated in chronic pruritus, allergy, and inflammation-related skin disorders." (PMID 33876725, 2021). "TRPV3 channel dysfunction caused by genetic gain‐of‐function mutations is implicated in the pathogenesis of skin inflammation, dermatitis, and chronic itch." (PMID 31710715, 2019). "Here, we bred NC/Nga-Nh congenic mice to test the ability of the mutated TRPV3 to cause AD-like dermatitis in an NC/Nga background." (PMID 19463197, 2009). "Recently, we have reported that Gly573Ser substitution in TRPV3 causes spontaneous hairless and dermatitis phenotypes in DS-Nh mice." (PMID 19463197, 2009). "The gain-of-function mutations in the TRPV3 channel not only lead to rodent hairlessness and dermatitis but also cause human-inherited skin disease Olmsted syndrome, characterized by keratoderma, dermatitis, hair loss, and severe itch." (PMID 39202808, 2024). "While being implicated in a variety of skin disorders, whether and how TRPV3 could be therapeutically targeted remains to be elucidated." (PMID 33876725, 2021). "These mutations drive constitutive TRPV3 activity under normal physiological conditions, subsequently altering ion homeostasis and membrane potentials of skin keratinocytes, leading to hair loss and dermatitis-like skin phenotypes." (PMID 30301231, 2018). "Adding further support to the role of TRPV3 in skin physiology and pathology, a TRPV3 gain-of-function G573S/C mutation was identified to underlie the spontaneously hairless, dermatitis phenotype of two rodent strains, DS-Nh mice and WBN/kob-HT rats, used as animal models of atopy." (PMID 27618069, 2016). "Moreover, the overactive TRPV3 function caused by either genetic gain-of-function mutations or skin sensitizers is implicated in the pathology of skin disorders such as hyperkeratosis, dermatitis, chronic pruritus, and abnormal hair growth." (PMID 38154600, 2023). "Compounds such as the TRPV1 blocker asivatrep and the TRPV3 inhibitor KM-001 have shown significant antipruritic effects in skin disorders, while tranilast, a TRPV2 antagonist, has provided concrete clinical evidence for TRP modulation in treating keloids." (PMID 41596464, 2026).